DUS4L-BCAP29 (DUS4L-BCAP29 readthrough)
Gene: Protein-coding gene on chromosome 7 (107,563,971 to 107,623,317, forward strand). Ensembl gene ENSG00000288558.
Genetic constraint (gnomAD): Loss-of-function variants: 39 observed, 40.93 expected, observed/expected ratio (o/e) 0.95, 90% interval 0.74 to 1.25. The upper end of that interval is the gene's LOEUF score, 1.25, which puts it in group 5 of 6, group 1 being the genes least tolerant of losing a copy. Missense variants: 446 observed, 460.86 expected, observed/expected ratio (o/e) 0.97, 90% interval 0.89 to 1.05. Synonymous variants: 135 observed, 151.41 expected, observed/expected ratio (o/e) 0.89, 90% interval 0.77 to 1.03.